IL22 (interleukin 22)
Diseases named in the same sentence as IL22 in open-access papers (continued):
Sharing a sentence is not in itself a finding about the gene and the disease.
psoriasis (continued). "In particular, serum levels of IL-17A were strongly correlated with IL-1α, IL-15, IFN-γ, IL-18, TNF-α, IL-12B, IL-17F, and IL-22 in psoriasis but not in healthy controls." (PMID 36118416, 2022). "IL-17A, IL-22, and IFN-γ can promote the abnormal proliferation of keratinocytes to form a positive feedback loop and continuously aggravate the inflammatory response of psoriasis." (PMID 35966027, 2022). "Different from the negative results of anti-IL-22 in psoriasis trials, ILV-094 seems attractive in AD therapeutics, as it improved SCORAD and neutrophils infiltration of asthma in severe AD patients in a preliminary study." (PMID 35911703, 2022). "Therefore, this study involved the use of IL-17A/IL-22/IFN-γ/TNF-α–induced HaCaT cells and mice with IMQ-induced psoriasis." (PMID 34456715, 2021). "Mixed cytokines, including IL-17A, IL-22, oncostatin M, IL-1α, and TNF-α (M5), are used to simulate HaCaT keratinocytes in vitro to establish a psoriatic keratinocyte model that generates some common phenotypic features of psoriasis." (PMID 34202301, 2021). "Therefore, we established psoriasis-like HPK by treating HPK with the cytokines IL-17A, TNF-α and IL-22." (PMID 33801280, 2021). "In conclusion, circ_0061012 contributed to IL-22-induced proliferation and motility of HaCaT cells through targeting miR-194-5p/GAB1 axis, providing a novel insight into developing new therapeutic targets for psoriasis patients." (PMID 33393621, 2021). "For example, activation of STAT3 by IL-22 is involved in the proliferation of keratinocytes, and activation of STAT3 by IL22 and IL-17A is involved in the induction of keratin 17, which is overexpressed in psoriasis." (PMID 34679602, 2021). "The inflammatory response in psoriasis is mainly driven by T cells, especially T helper cells (Th17), and is mediated by different cytokines, especially TNF-α, IL-17, IL-23 but also other cytokines such as IFN-γ, IL-2, IL-6, IL-8, IL-17, IL-18 and IL-22." (PMID 34640327, 2021). "Unexpectedly, the weights of IL-17, IL-22, and IL-23 were decreased that were correlated to the interaction between the interleukin family, or the specificity of interleukins in psoriasis is actually not high." (PMID 33959184, 2021). "Among T lymphocyte-derived cytokines related to psoriasis, TNF-α is the main cytokine trigger of PI3Kδ expression, although IL-22 also sustains PI3Kδ levels in human keratinocytes, supporting a role for PI3Kδ in proliferation and de-differentiation processes induced by IL-22 in diseased skin." (PMID 34685616, 2021). "Cytokines such as IFN-γ, IL-17A or IL-22 bind to cell surface receptors and the signal transduction occurs through JAKs, which in turn promotes STAT1 and/or STAT3 phosphorylation and activation in psoriasis." (PMID 33986690, 2021). "Although these two isoforms are equally expressed in ACT1D10N/D10 fibroblasts, ACT1D10N/D10 T cell expressed predominantly ACT-D10N, leading to a dysregulated hyperactive TH17 response with elevated IL-17A and IL-22 expression in ACT1D10N/D10 T cells and consequently severe psoriasis." (PMID 34777377, 2021). "Mixed cytokines, including IL-17A, IL-22, oncostatin M, IL-1α, and TNF-α (M5), were used to simulate HaCaT keratinocytes to establish a psoriatic keratinocyte model that generates some phenotypic features in common psoriasis in vitro." (PMID 34202301, 2021). "Psoriasis is a hyperproliferative skin disease with a predominant Th1/Th17 response, with an upregulated concentration of multitude cytokines (TNF-α, IL-1β, IL-12, IL-17A, IL-22, IL-23, interferon-γ, and IL-13)." (PMID 34685480, 2021). "Treatment with LEU, but not VER and HP extract improved psoriasis-related inflammation via suppression of the PI3K/AKT signaling in IFN-γ/IL-17A/IL-22-stimulated HaCaT cells." (PMID 34834106, 2021). "Considering the role of IL-22, it can no longer be denied that psoriasis is a Th1/Th17/Th22-mediated autoimmune disease." (PMID 34975883, 2021).
psoriasis (continued). "In addition, IL-22 induces STAT3 phosphorylation; this is related to the induction of acanthosis (keratinocyte proliferation) and dermal inflammation in psoriasis." (PMID 34943117, 2021). "On the other hand, upon stimulation with IL-22 the activated keratinocytes respond through STAT3 up-regulation and changes in their differentiation profile toward hyper-keratinization and hyperproliferation as hallmarks of psoriasis." (PMID 33986690, 2021). "Moreover, sensors can cure psoriasis through sensing TNF-a and IL-22 as biomarkers of psoriasis with the following expression of the therapeutic cytokines IL-4 and IL-10." (PMID 34829757, 2021). "The psoriasis pathogenesis depends on environmental and genetic factors and involves communication between different immune cells through cytokines such as tumor necrosis factor-α (TNFα), IFN-γ, IL-17, IL-22 and IL-23." (PMID 34445713, 2021). "In addition, Th17 responses are involved in IMQ-induced psoriasis-like lesions, and the combination of Acar and low-dose CsA could significantly modulate the serum and skin expression levels of Th17 cytokines (IL-17A, IL-22, and IL-23) compared with Acar alone or low-dose CsA alone." (PMID 32316255, 2020). "Finally, we generated psoriasis-like keratinocytes by treating HPKs with cytokines that are involved in the pathogenesis of psoriasis (IL-17, TNF-α, IL-22 and IFN-γ), and studied the effects of GE treatment on the expression of ELOVLs and CERS3." (PMID 32316273, 2020). "Interestingly, medium and high doses in G3–G4, with comparatively low levels of IL-22 and TNF-α, showed stronger anti-psoriasis-like symptoms." (PMID 33253155, 2020). "In this study, we explored several factors that contributed to psoriasis, such as TNF-α, IL-17A, and IL-22 and found that chrysin could ameliorate the inflammatory reactions induced by these factors." (PMID 32076123, 2020). "Thus, this “cytokine converter” exerts its function only when both TNF and IL22 coexist (AND-gate logic), which is a characteristic of psoriasis." (PMID 32185403, 2020). "The mixture of IL-17A, IL-22, oncostatin M, IL-1α, and TNF-α (M5) cytokines were used to simulate HaCaT keratinocytes to establish psoriatic keratinocyte model recapitulating some features of psoriasis in vitro." (PMID 33081840, 2020). "Expression of IL-22 rather than IL-17 is predominant in AD skin, which is contrary to cytokine expression in psoriasis skin." (PMID 32075269, 2020). "In psoriasis, TNFα, and inducible nitric oxide synthase (iNOS)-producing DCs (Tip-DCs) and 6-sulfo LacNAc DCs (slanDCs) are reported as iDCs, and they induce T cells to secrete IL17, IL22, TNFα, and IFNɤ." (PMID 33050592, 2020). "Anti-IL-22 antibody is not effective in psoriasis, and anti-IL12/23p40 or anti-IL-17A antibodies are not promising as treatment for AD." (PMID 32075269, 2020). "Previous studies demonstrated that the pro-inflammatory cytokines, including TNF-α, IL-6, IL-1β, IL-17A, and IL-22 were up-regulated in psoriatic skin tissues and serum, and the IL-23/IL-17 axis was found to participate in the regulation of IMQ-induced psoriasis-like skin inflammation." (PMID 32515468, 2020). "IL-17, IL-22, and IL-23 have been reported to play an important role not only in psoriasis but also in other autoinflammatory disorders." (PMID 32823524, 2020). "Taken together, IL-22 rather than IL-17 is dominant in AD skin, while IL-17 is dominant in psoriasis skin." (PMID 32075269, 2020). "In psoriasis, CD4+ cells are the main source of IL-17 and IL-22." (PMID 32316255, 2020). "Therefore, the regulatory mechanism of IL-22 on anti-apoptosis of keratinocytes occurs in the presence of TNF-α and IFN-γ in psoriasis." (PMID 32632545, 2020). "We determined the mRNA expression levels of several inflammatory cytokines that are important in psoriasis (TNF-α, IL-23p19, IL-17A, IL-22, IFN-α, IL-1β, IL-6, and IL-10) and a chemokine that promotes the migration of neutrophils (CXCL2) using quantitative real-time PCR." (PMID 32752186, 2020).
psoriasis (continued). "Groups that have been treated with Dysidea avara methanolic extracts are most active in reducing symptoms of induced psoriasis by decreasing amounts of IL-22, IL-17A, TNF-α, and decreasing neutrophils” infiltration into the epidermis, which is important in psoriasis’s pathogenesis." (PMID 33253155, 2020). "Our data did not support the existence of a dual-secreting IL-17A/IL-22 Th17 cell as the major source of these cytokines in psoriasis." (PMID 31019502, 2019). "CDC6 expression is upregulated in epidermal cells in psoriatic lesions and it could be induced by IL-22/STAT3 signaling, a key signaling pathway involved in the pathogenesis of psoriasis, in keratinocytes." (PMID 30894513, 2019). "Increased levels of TNF, IL-1β, and IL-22 augment the inflammatory effects of IL-17 by enhancing the expression of TNF receptors, suggesting a synergistic interplay between these cytokines in psoriasis pathogenesis." (PMID 31295952, 2019). "Several classes of biologicals have been developed against inflammatory cytokines, including TNF-α, IL-22, IL-23, and IL-17, although they are not effective in all individuals with psoriasis." (PMID 31252620, 2019). "Taken together, these results do not support the current dogma that IL-17A/IL-22 dual-secreting Th17 T cells are the major driver of psoriasis pathophysiology." (PMID 31019502, 2019). "In addition to this axis representing the core of psoriasis pathogenesis, upstream cytokines (IFN-α, IFNγ, and TNFα), synergizing cytokines (IL-22 and TNFα), and downstream mediators (IL-8, IL1F9, and CCL20) complete the pathogenic puzzle." (PMID 29316717, 2018). "Nevertheless, IL-22 likely results pathogenically more relevant in animal models of psoriasis and in vitro, rather than in vivo." (PMID 29316717, 2018). "During the chronic phase of psoriasis, expansion and activation of T and DC subpopulations in lesional areas establishes a definite cytokine micromilieu, mostly represented by IFN-γ, IL-17, TNF-α, and IL-22." (PMID 30034395, 2018). "IL-17A acts in synergism with other key-cytokines in psoriasis such as TNF-α and IL-22, stimulating the expression AMPs (LL37, β-defensins, LCN2, S110A family proteins), inflammatory cytokines (IL-1 family members and IL-6), and chemokines (CXL1, -3, -5, -8, and CCL20)." (PMID 29316717, 2018). "Moreover, followingstimulation of STAT3 phosphorylation by IL-6/IL-22, the ensuing signaling pathwayleads to overexpression of VEGF during psoriasis." (PMID 29630472, 2018). "In an etanercept trial, a subset of inflammatory genes that contribute to psoriasis pathogenesis, including IL-12p35, IL-22, IL-17, and IFN-γ, did not return to non-lesional levels." (PMID 30109481, 2018). "Secretion of IL-17, IL-21, and IL-22 by TH17 cells correlates with the pathogenesis of several autoimmune (rheumatoid arthritis, systemic lupus erythematosus, multiple sclerosis, and psoriasis) and inflammatory diseases (inflammatory bowel disease and allergy and asthma)." (PMID 29632528, 2018). "Moreover, IL-22 induces psoriasis like skin changes and its blockade can be as effective as anti-TNF in a psoriasis model." (PMID 29163483, 2017). "Additionally, the inverse relationship between IL-22 and IFN-γ was described in patients with active psoriasis." (PMID 28855908, 2017). "Moreover, they contribute to other autoimmune diseases such as psoriasis in which epidermal CCR6+ Vδ2+ cells express high levels of IL-17 and IL-22." (PMID 28076364, 2017). "As a result of the migratory potential and the ability of the Lin− CD123low CD127int population present in CS to express IL-17 and IL-22, the frequencies and the expression of these cytokines by the ILC-related populations from psoriasis patients were subsequently assessed." (PMID 28303135, 2017). "Remarkably, the CD123low population in the lesion and non-lesion skin of psoriasis patients expresses IL-17 and IL-22." (PMID 28303135, 2017).
psoriasis (continued). "In addition, psoriasis-related cytokines, including IFN-γ, TNF-α, IL-17 and IL-22, induced IFI16 up-regulation in keratinocytes via activation of STAT3 signaling." (PMID 27137868, 2016). "Additionally, the detection of mouse IL22 by antibody 30G1 offered an opportunity to measure its bio-activity toward endogenous IL22, a primary effector of imiquimod (IMQ)-induced dermatitis used to model psoriasis." (PMID 27426947, 2016). "In vitro results showed that several psoriasis-related cytokines, including IFN-γ, TNF-α, IL-17 and IL-22, could up-regulate IFI16 expression in keratinocytes via activation of STAT3 signaling." (PMID 27137868, 2016). "Psoriasis is characterized by over-proliferation and/or disturbed differentiation of keratinocytes, as well as by enhanced expression of tumor necrosis factor-α (TNF-α), IL-17 and IL-22 within the psoriatic skin." (PMID 26474319, 2015). "Although our results do not show any correlation between serum levels of IL-17A, IL-22, and IL-6 and disease activity, the present study confirms that they were increased in Brazilian psoriasis patients in comparison to healthy volunteers." (PMID 26351408, 2015). "In the psoriasis lesions, the production of IL23 bydendritic cells and keratinocytes is increased, stimulating Th17 cells withinthe dermis to produce "Th17 cytokines", which includes IL-17A, IL-17F,TNF-alpha, IL-21, and IL-22." (PMID 26734868, 2015). "In contrast to IL-17 and IL-22, which suppressed chemerin expression, OSM and IL-1β significantly increased chemerin production, despite the fact that all four cytokines are potent keratinocyte activators with potential roles in the pathology of psoriasis." (PMID 25659101, 2015). "Immune/inflammatory parameters including IL-6 and IL-22, CLA+ T cells, and Treg lymphocytes may prove to be valuable laboratory tools for the clinical and therapeutic monitoring of psoriasis." (PMID 25136144, 2014). "In light of our findings, we can hypothesize the employment of DCE and CS in psoriasis might counteract the pro-inflammatory effects of IFN-γ and IL-22 on keratinocytes, as well as to inhibit hyperproliferation in the psoriatic epidermis." (PMID 25226283, 2014). "Our data thus confirm the involvement of Th22 cells in psoriasis, as recently suggested by other authors which also found increased serum levels of IL-22 in the presence of anincrease of IL-6 and in the absence of IL-17 increments." (PMID 25136144, 2014). "In the absence of IL-22, severity of both IL-23-mediated and imiquimod-induced psoriasis-like dermatitis in corresponding mouse models is markedly reduced." (PMID 25126586, 2014). "Psoriasis is thought to develop and be maintained as a result of cooperative efforts of several T cell cytokines in addition to IL-17, namely IFN-γ and IL-22, which augments cellular recruitment through chemokine induction and stimulates epidermal hyperplasia, respectively." (PMID 24587313, 2014). "Much debate exists regarding the relative contribution of CD8+ T cells to cytokine production in psoriasis, as CD8+ T cells may also produce IL-17 and IL-22." (PMID 23468834, 2013). "However, R348 does not induce hypercholesterolemia and reduces systemic levels of IL17, IL22, IL23, and TNF, which are important for controlling psoriasis." (PMID 24170986, 2013). "Several cytokine genes with overall low expression but high differential effect in psoriasis (IFNG, IL12B, IL17F, and IL22) displayed higher magnitude changes with cDNA than with cRNA hybridization, whereas the highly expressed gene IL1F9 showed a higher magnitude change with cRNA hybridization." (PMID 23308107, 2013). "Although mice with epidermal acanthosis and dermal inflammation induced by IL-23 injection into the ear are not an exact model for psoriasis, many of the features in this model, such as IL-22 upregulation and STAT3 activation, are similar to the features evident in psoriasis." (PMID 23956763, 2013).
psoriasis (continued). "IL-22 is a member of the IL-10 family, mainly produced by T cells and natural killer (NK) cells and represents an effector cytokine of the TH17 lineage that mediates immunopathology in inflammatory diseases, such as psoriasis or arthritis." (PMID 23460846, 2013). "We also assessed functionality of the T cells by evaluating the secretion of several inflammatory cytokines (IL-17A, IFN-gamma, IL-2, IL-33, TNF-alpha, IL-21, IL-22, and IL-27), from cell-sorted purified CD4+ and CD8+ T cells isolated from lesional and unaffected skin biopsies of psoriasis patients." (PMID 23468834, 2013). "Here we show that in keratinocytes GATA3 is strongly induced by IL-4.Psoriasis is currently viewed as a predominantly Th1/Th17 disease, where the Th1cytokines (IFN-γ) and Th17 cytokines (IL-17, IL-22) together with IL-23 suppressthe production of IL-4 in T lymphocytes." (PMID 21611195, 2011). "Notably, aberrant methylation patterns of IL-17, IL-21, and IL-22 are not exclusive to GD; similar patterns have been reported in other Th17-mediated autoimmune diseases, including rheumatoid arthritis, psoriasis, and Sjögren’s syndrome." (PMID 41035651, 2025). "It has been found that IL-22-mediated downregulation of microflora such as segmented filamentous bacteria (SFB) is related to impairment of systemic aberrant Th17 responses and development which are involved in the pathogenesis of autoimmune diseases like IBD, rheumatoid arthritis and psoriasis." (PMID 41467015, 2025). "Our results showed a significant attenuation of psoriasis symptoms (erythema, scaling, and skin thickness) in mice treated with intact hUCB-MSCs, hUCB-MSCs preconditioned with IL-22 and TNF-α, and hUCB-MSC-Exo preconditioned with IL-17, IL-22 and TNF-α (MSC-Exo 3C)." (PMID 40906403, 2025). "It has been shown that a mixture of IL-17, IL-22, and TNF-α resulted in destabilization of the epidermis, parakeratosis, and hypogranulosis, resembling partially the lesional psoriasis phenotype, and several 3D models have been proposed to study psoriasis features." (PMID 40243580, 2025). "Here, we investigated the expression of psoriasis-related cytokines (TNF-α, IL-6, IL-22, IL-23, IL-17A, IL-17E, IL-17F, IL-4 and IL-10) in the inflamed skin after mannan exposure at the peak (day 4) and the end (day 7) of psoriasis with/without inhibitor(s) treatment." (PMID 38444844, 2024). "In psoriasis, MIR31HG was found to be elevated in psoriasis lesions and the upregulation of MIR31HG required IL-17A, IL-22, TNF-α, and IL-1α stimulation, demonstrating that nuclear factor kappa B inhibitor (NF-κB) signalling could be crucial crosstalk in psoriasis." (PMID 37636269, 2023). "In addition, the HA-ES group loaded with CUR showed relief of inflammatory symptoms according to the clinical psoriasis area and severity index (PASI), lower levels of TNF-α, IL-17A, IL-17F, IL-22, and IL-1β mRNA, and lower CCR6 protein expression compared to ES and PGS groups." (PMID 36678859, 2023). "Conversely to psoriasis, HS keratinocytes exhibited a significant lower level of VEGF, as well as IL-1α and IL-22 compared to normal keratinocytes using an in vitro scratch assay, which suggests that changes in VEGF signaling may be associated with HS pathogenesis." (PMID 37176138, 2023). "Furthermore, ACC1 is required to upregulate IL-22 expression levels in RORγt+ innate lymphoid cells (ILC3), which may also promote inflammation in psoriasis." (PMID 37594540, 2023). "Similarly, Cordero discovered higher IL-22-expressing T cells in pediatric psoriasis patients rather than adult ones." (PMID 35911703, 2022). "In addition, curcumin has also been demonstrated to be effective as an adjuvant therapy for psoriasis, reducing skin inflammation and serum IL-22 levels, these effects being independent of its senolytic activity." (PMID 36142384, 2022).